RAI14 (retinoic acid induced 14)
Diseases named in the same sentence as RAI14 in open-access papers (continued):
Sharing a sentence is not in itself a finding about the gene and the disease.
tumor (continued). "To further validate the effect of RAI14 on tumor growth, we detected Ki67, RAI14, FBXO32 and c-MYC by using immunohistochemistry." (PMID 36233342, 2022). "Subsequently, tumorigenesis in vivo was impaired by RAI14 depletion, as evidence by dampened tumor growth." (PMID 32228518, 2020). "A xenograft tumor experiment in nude mice was conducted to verify the potential effect of RAI14 on EC." (PMID 32957082, 2020). "Thirty-three days after inoculation, the tumor volume in the RAI14-silencing group (siRAI14-2) was decreased as compared with that in control group." (PMID 32957082, 2020). "All in all, these findings unveiled that RAI14 binds with miR-653-5p and its depletion impairs tumor growth." (PMID 32228518, 2020). "In the current study, the phosphorylation of STAT3 was suppressed when RAI14 was silenced in EC cells, and this suppression impeded tumor progression." (PMID 32957082, 2020). "Inhibition of STAT3 restored the oncogenic effect of RAI14, and RAI14 silencing restrained tumor growth and the protein level of Ki67 in vivo." (PMID 32957082, 2020). "Furthermore, in situ transplantation of Hep-53.4 cells with Rai14 knockout into the liver led to inhibited tumor growth and extended survival, with the inverse observed upon overexpression." (PMID 41361104, 2025). "Thus, RNASEH2C advanced tumor progression by promoting RAI14 lysosomal degradation, with HSC70 and CMTM6 playing key roles." (PMID 41361104, 2025). "Subsequently, we investigated the role of RAI14 in the polarization of macrophages and assessed whether its tumor-regulating effects are exclusively dependent on immune mechanisms." (PMID 41361104, 2025). "Moreover, the expression of RAI14 in tumor cells is positively correlated with the number of fibroblasts and myo-fibroblasts." (PMID 36934880, 2023). "Patients with larger tumor diameters had higher RAI14 levels (p = .0081, r = 0.245)." (PMID 36880986, 2023). "Through correlation analysis of the clinicopathological factors, it was found that the concentration of RAI14 was positively correlated to tumor volume, CA15-3 and LDH serum levels, which means patients with a larger tumor volume were more likely to have higher RAI14 levels." (PMID 36880986, 2023). "Also, the expression of RAI14 was significantly different among different disease stages and tumor grading." (PMID 35431930, 2022). "It means that knocking down RAI14 inhibits tumor growth in vivo." (PMID 36233342, 2022). "Therefore, knocking down STAMBP resulted in the reduction in RAI14 protein levels and suppression of tumor growth in vitro and in vivo." (PMID 36434041, 2022). "In this study, our unbiased siRNA and substrate screening revealed a previously unknown role of STAMBP in TNBC: STAMBP direct removes ubiquitin from RAI14, enhancing the stability of tumor-promoting RAI14." (PMID 36434041, 2022). "Many recent studies have explored the mechanism of RAI14 on tumor growth." (PMID 36233342, 2022). "We also explored the effect of RAI14 on tumor growth in vivo by subcutaneous xenograft assay." (PMID 36233342, 2022). "In summary, our results suggest that RAI14 is a tumor promoter of EC." (PMID 32957082, 2020). "We noticed that RAI14 depletion remarkably restrained the tumor size, volume and weight of mice." (PMID 32228518, 2020). "However, all current studies on RAI14 were conducted in tumor tissues and cell lines." (PMID 36880986, 2023). "Our research has thus far concentrated solely on the role of RAI14, leaving the involvement of PRDX1 in RNASEH2C-mediated tumor regulation unclear." (PMID 41361104, 2025). "Thus, we suggest that the upregulation of RAI14 may contribute to tumor progression." (PMID 36880986, 2023). "Besides, miR-653-5p overexpression or RAI14 inhibition could repress tumor growth." (PMID 32228518, 2020).
tumor (continued). "The integration from our omics-based research provides a four molecular pathway foundation (ANXA2/HMGA1/POU3F1; NFRSF13/GSN; TMOD3/RAI14/VWF; and PLAT/PLAU) behind HO-1 regulation of tumor cytoskeletal cell compartments." (PMID 28032857, 2016). "Next, we validated our results using clinical tissue samples from GC patients (8 IGC and 8 DGC) and found that the protein level of RAI14 was upregulated in most tumor tissues regardless of tumor histology." (PMID 39160347, 2024). "Dynamic changes of RAI14 levels represent a precise parameter for the early treatment of TNBC and provide a more direct and reliable reference for efficacy assessment in comparison to the determination of CA15-3 levels and tumor diameter." (PMID 36880986, 2023). "Strikingly, when integrating the transcriptome under HO-1 modulation with the HO-1 interactome, a framework of four main molecular pathways arose as the foundation for the regulation of the tumor cell protrusive forces: ANXA2/HMGA1/POU3F1; NFRSF13/GSN; TMOD3/RAI14/VWF; PLAT/PLAU." (PMID 28032857, 2016). "However, no statistical differences were seen in RAI14 levels in BC patients with a variety of clinical stages and lymph node metastasis status in this study; therefore, whether the expression of RAI14 relates to the stage of BC tumor development deserves more attention in our follow-up studies." (PMID 36880986, 2023).
cancer (12 papers, 2019 to 2024). A tumor composed of atypical neoplastic, often pleomorphic cells that invade other tissues. "Our data show that the cancer-promotive function of RAI14 is strongly associated with Hippo signaling and YAP activity." (PMID 39160347, 2024). "Recent studies have found that RAI14 is highly expressed in several types of cancer and is associated with cancer prognosis." (PMID 36233342, 2022). "In addition, we found that increased RAI14 promoted APC-MUT cancer cell migration by remodeling the cell adhesion–associated phosphoproteome, suggesting that RAI14 and related regulators are potential targets for treating malignant APC-MUT tumors." (PMID 36934880, 2023). "Next, to determine the role of endogenous RAI14 in cancer cells, we generated stably expressing shRAI14 in SNU638 GC cells." (PMID 39160347, 2024). "Our data suggest that RAI14 links mechanotransduction with Hippo signaling and mediates Hippo-related biological functions such as cancer progression." (PMID 39160347, 2024). "Recent studies showed that RAI14 is overexpressed in gastric, esophageal, ovarian, lung cancer, and other malignant tumors with a significant role in the development of tumors." (PMID 36880986, 2023). "Collectively, these results demonstrate that RAI14 is an important protein involved in the regulation of cancer cell migration." (PMID 36934880, 2023). "This relationship between RAI14 and immune infiltration suggested that they were possibly relevant to cancer oncogenesis and development." (PMID 35431930, 2022). "RAI14 expression and prognosis were correlated with the subclass, histological type, cancer stage, menopause status, age, estrogen receptor (ER), and triple-negative status." (PMID 35431930, 2022). "Ki67 functions as a proliferation marker in cancer, and the levels of RAI14 and Ki67 were significantly decreased in the xenograft tumors in the RAI14-knockdown mice as compared with those in the xenograft tumors in the control mice (P < 0.05 vs. siNC)." (PMID 32957082, 2020). "The biological role of RAI14 is primarily related to cancer progression and neuronal function." (PMID 39160347, 2024). "In addition to cancer progression, RAI14 promotes neuronal function by regulating dendritic arborization and neuronal morphogenesis." (PMID 39160347, 2024). "However, little is known about how RAI14 promotes cancer progression and the signaling pathways involved in this process." (PMID 39160347, 2024). "EMT is known to maintain cancer development and metastasis; therefore, we further examined whether RAI14 regulates the EMT in TNBC." (PMID 36434041, 2022). "Therefore, we propose that RAI14 may be one of the players in regulating YAP by responding to tissue stiffness during cancer progression." (PMID 39160347, 2024). "Also, RAI14 is a promising potential therapeutic target for cancer therapy." (PMID 35431930, 2022). "Although retinoic acid induced 14 (RAI14) is involved in various cancer processes, the relationship between EC and RAI14 has not been elucidated." (PMID 32957082, 2020). "Although the discovery of AFAP1-AS1/miR-653-5p/RAI14 axis may enrich the study of AFAP1-AS1 in cancers, the lack of novelty in mechanistic insight is the major limit of this work, which we would improve in further studies." (PMID 32228518, 2020). "Retinoic acid induced 14 (RAI14) was originally identified in all-trans retinoic acid-induced human retinal pigment epithelial cells, RAI14 may be connected to the growth and invasion of cancer cells in several malignancies, according to current investigations." (PMID 36159818, 2022).
RAI14 also shares sentences with these, for which no sentence is quoted: ovarian carcinoma (4 papers); psoriasis (2); Anxiety (1); benign breast disease (1); invasive lobular carcinoma (1); liver cancer (1); nevus (1); osteosarcoma (1).